NEK8 (NIMA related kinase 8)
Description:
Required for renal tubular integrity. May regulate local cytoskeletal structure in kidney tubule epithelial cells. May regulate ciliary biogenesis through targeting of proteins to the cilia. Plays a role in organogenesis, and is involved in the regulation of the Hippo signaling pathway.
Synonyms: JCK; NEK12A; NPHP9; PKD8; RHPD2
Tractability: Small molecule: a high-quality ligand is known; it belongs to a druggable protein family. PROTAC: ubiquitination databases record sites on it; a small molecule that binds it is known.
Target class: Other protein kinase NEK family; Kinase; Enzyme; Other protein kinase group; Protein Kinase
Gene: Protein-coding gene on chromosome 17 (28,725,897 to 28,743,455, forward strand). Ensembl gene ENSG00000160602.
Subcellular location: Cytoplasm; Cytoplasm, cytoskeleton; Cell projection, cilium; Cytoplasm, cytoskeleton, microtubule organizing center, centrosome; Cytoplasm, cytoskeleton, cilium axoneme
Subcellular location (Human Protein Atlas): Microtubules; Mitotic spindle; Nuclear speckles; Primary cilium
Gene Ontology:
Molecular function: protein binding; protein serine/threonine kinase activity; ATP binding; protein kinase activity; protein serine kinase activity
Biological process: animal organ morphogenesis; regulation of hippo signaling; determination of left/right symmetry; heart development; animal organ development
Cellular component: cilium; cytoplasm; axoneme; centrosome; ciliary base; ciliary inversin compartment; cytoskeleton
Genetic constraint (gnomAD): Loss-of-function variants: 51 observed, 77.17 expected, observed/expected ratio (o/e) 0.66, 90% interval 0.53 to 0.83. The upper end of that interval is the gene's LOEUF score, 0.83, which puts it in group 3 of 6, group 1 being the genes least tolerant of losing a copy. Missense variants: 787 observed, 945.96 expected, observed/expected ratio (o/e) 0.83, 90% interval 0.78 to 0.88. Synonymous variants: 365 observed, 381.77 expected, observed/expected ratio (o/e) 0.96, 90% interval 0.88 to 1.04.
Gene-disease validity (ClinGen):
ClinGen rates the evidence that NEK8 causes each of these diseases.
renal-hepatic-pancreatic dysplasia 2 (autosomal recessive): Definitive. Any renal-hepatic-pancreatic dysplasia in which the cause of the disease is a mutation in the NEK8 gene.
autosomal dominant polycystic kidney disease (autosomal dominant): Strong. Autosomal dominant form of polycystic kidney disease.
Homologues: Orthologues: chimpanzee NEK8 (99% identical), macaque NEK8 (98% identical), pig NEK8 (95% identical), guinea pig NEK8 (95% identical), dog NEK8 (94% identical), rabbit NEK8 (94% identical), mouse Nek8 (94% identical), rat Nek8 (94% identical), tropical clawed frog nek8 (76% identical), zebrafish nek8 (74% identical). Paralogues in human: NEK9 (32% identical), NEK5 (23% identical), NEK11 (20% identical), NEK3 (19% identical), NEK2 (18% identical), NEK10 (17% identical), NEK7 (15% identical), NEK6 (15% identical).
Diseases named in the same sentence as NEK8 in open-access papers:
NEK8 is named in the same sentence as 64 diseases in open-access papers, as found by Europe PMC text mining. Sharing a sentence is not in itself a finding about the gene and the disease. The quoted sentences say what the papers report.
breast carcinoma (12 papers, 2010 to 2025). "However, only a few studies have investigated the function of NEK8 in breast cancer cells and its underlying molecular mechanisms." (PMID 37100815, 2023). "NEK8 encodes a member of the serine/threonine protein kinase family, which plays a role in cell cycle progression from G2 to M phase and is over-expressed in breast cancer." (PMID 21172017, 2010). "NEK8 overexpression plays a direct role in the proliferation and invasiveness of many breast cancers." (PMID 39975112, 2025). "NEK8 is overexpressed in breast cancer, but the impact of NEK8 overexpression on homologous recombination has not been determined." (PMID 39975112, 2025). "Future work will need to be conducted to determine how breast cancer cells with elevated NEK8 respond to PARP inhibition." (PMID 39975112, 2025). "Our study reveals new perspectives on the interplay between NEK8 and β-catenin in breast cancer cells, highlighting the crucial role of NEK8 in promoting malignancy through the activation of β-catenin signalling in breast cancer initiation and advancement." (PMID 37100815, 2023). "To identify differential NEK8 mRNA expression, we examined a panel of breast cancer cell lines and the normal breast epithelial cell line MCF10A." (PMID 37100815, 2023). "This indicated that NEK8 affects breast cancer metastasis by regulating the expression of genes related to proliferation, EMT, and stemness." (PMID 37100815, 2023). "To elucidate the function of NEK8 in the modulation of breast cancer cell proliferation, we used small interfering RNA (siRNA)-directed knockdown to deplete NEK8 expression in breast cancer cell lines overexpressing NEK8." (PMID 37100815, 2023). "Overall, our findings suggest that NEK8 has a direct impact on maintaining β-catenin stability and thereby, in activating Wnt/β-catenin signalling in breast cancer cells." (PMID 37100815, 2023). "To determine the clinical relevance of NEK8 in breast cancer, we evaluated NEK8 mRNA expression patterns using data from the Oncomine, Gene Expression Profiling Interactive Analysis (GEPIA), and TNMplot databases." (PMID 37100815, 2023). "Earlier studies have demonstrated that NEK8 exhibits heightened expression levels in breast cancer, contributing to its overexpression." (PMID 37596667, 2023). "In the Oncomine breast cancer datasets, NEK8 mRNA expression was 1.450-fold higher in invasive breast carcinoma samples than in normal tissues (P = 1.34e−5)." (PMID 37100815, 2023). "In the breast invasive carcinoma database from GEPIA, NEK8 mRNA expression was significantly higher in breast cancer tissues than in normal tissues." (PMID 37100815, 2023). "Using the Oncomine and TNMplot public databases, we found a significant correlation between NEK8 overexpression and poor clinical outcomes in breast cancer patients." (PMID 37100815, 2023). "We evaluated the impact of NEK8 knockdown on breast cancer cell proliferation in a 3D culture system that mimics tumour growth in vivo." (PMID 37100815, 2023). "To evaluate the function of NEK8 in CSCs derived from breast cancer cell lines, including MDA-MB-231, BT549, and HCC38 cells, we enriched CSCs by culturing the cells in mammosphere media under non-adherent conditions to form unattached tumour spheres." (PMID 37100815, 2023). "In this study, we found that NEK8 expression was higher in breast cancer cell lines than in normal cell lines." (PMID 37100815, 2023). "According to our ongoing research and an analysis of public databases, there is a significant upregulation in NEK8 expression in breast cancer cells." (PMID 37100815, 2023). "After observing that NEK8 knockdown decreased the proliferation, migration, invasion, and stemness of cultured breast cancer cells, we assessed the functional effects of NEK8 in controlling tumour growth in a murine xenograft model." (PMID 37100815, 2023).
breast carcinoma (continued). "NEK8 knockdown in breast cancer cell lines significantly inhibited cell proliferation, migration, invasiveness, stemness, and cisplatin chemoresistance in vitro." (PMID 37100815, 2023). "Results from RT-PCR and western blotting analysis showed an upregulation of NEK8 mRNA and protein expression in breast cancer cell lines compared to the normal breast epithelial cell line, MCF10A." (PMID 37100815, 2023). "The expression of NEK2, NEK6, and NEK11 were related to colorectal cancer, NEK2, NEK3, NEK5, NEK6, and NEK8 to breast cancer, and NEK2 and NEK6 to prostate cancer." (PMID 31906878, 2020). "Nek8 is upregulated in primary human breast tumors, and the ectopic overexpression of Nek10 has been found in breast cancer." (PMID 25120679, 2014). "Next, we assessed the impact of NEK8 on the expression of EMT markers in breast cancer cells." (PMID 37100815, 2023). "Our findings support the hypothesis that increased NEK8 expression plays a crucial role in breast cancer cell growth and metastasis." (PMID 37100815, 2023). "Our research found that β-catenin is a crucial downstream mediator of NEK8 in breast cancer." (PMID 37100815, 2023). "Additionally, a previous study has reported the role of NEK8 in regulating breast cancer cell growth and mobility through the transcriptional coactivator with PDZ-binding motif (TAZ) pathway." (PMID 37100815, 2023). "Thus, to examine the role of NEK8 in cell cycle regulation in breast cancer, we investigated the effect of NEK8 knockdown on the expression of cell cycle-related genes." (PMID 37100815, 2023). "NEK8 is highly expressed in various types of invasive breast cancer, and our findings indicate a link between high expression levels and poor OS in breast cancer patients, as suggested by analysis of public databases such as Kaplan–Meier plotter and the Oncomine database." (PMID 37100815, 2023). "Furthermore, to determine the role of NEK8 in the promotion of stemness of breast cancer cells in vivo, we conducted xenograft experiments with MDA-MB-231 cells using a limited dilution xenograft assay." (PMID 37100815, 2023). "Furthermore, NEK8 is known to play a role in gastric cancer cells and breast cancer, while NEK11 is known to play a role in ovarian cancer." (PMID 34834441, 2021). "Furthermore, NEK8 has been found to impact the progression of breast cancer and glioma." (PMID 37596667, 2023). "Also, cell cycle arrest was prominent in breast cancer cells transfected with NEK8 siRNAs." (PMID 37100815, 2023). "Thus, NEK8 may be a crucial regulator of breast cancer progression and a potential therapeutic target." (PMID 37100815, 2023). "Hence, targeting NEK8 could be a promising approach for breast cancer treatment." (PMID 37100815, 2023). "The expression level of NEK6 in breast cancer cells (MCF-7 and SK-BR-3) was higher than that in normal breast epithelial cells in MCF-10A, and the expression level of NEK8 and NEK11 was higher than that in normal epithelial cells in MCF-7 (p < 0.01)." (PMID 35368696, 2022). "The mRNA level analysis of NEK genes in breast cancer cell lines and breast cancer patients from various data sources revealed that NEK2, NEK4, NEK5, NEK6, NEK8, and NEK11 are overexpressed in breast cancer and may be involved in breast cancer development." (PMID 37627077, 2023). "Furthermore, it was shown that NPHP9 (NEK8), which is upregulated in breast cancer, modulates cilia length and activates the oncogenic Hippo pathway transcription factor TAZ." (PMID 23628112, 2013). "Thus, non-specific breast cancers containing increased NEK8 expression may be sensitive to PARP inhibitors." (PMID 39975112, 2025).
ciliopathies (11 papers, 2015 to 2025). "Previous research has also explored the broader implications of NEK8 mutations beyond the ciliopathies." (PMID 41154634, 2025). "Other NEK family members (e.g., NEK1, NEK4, and NEK8) were identified as causal factors in mouse models of polycystic kidney disease or have been linked to human ciliopathies." (PMID 37099601, 2023). "NEK8 is also important for primary cilium stabilization; thus, ciliopathies are directly associated with NEK8." (PMID 32294979, 2020). "In summary, the literature shows that NEK8 is associated with diseases such as ciliopathies, including nephronophthisis (NPHP), polycystic kidney disease, and cancer." (PMID 32294979, 2020). "Here we report novel NEK8 mutations in patients with renal cystic hypodysplasia and associated ciliopathy defects." (PMID 26967905, 2016). "Valentina Grampa (same group) won a best poster award reporting her work identifying several recessive NEK8 mutations in patients with severe ciliopathies." (PMID 25974046, 2015). "We also review the literature about the pathological consequences of different NEK8 variants in patients of nephronophthisis, renal-hepatic-pancreatic dysplasia and autosomal dominant polycystic kidney disease, three different types of ciliopathies." (PMID 40189576, 2025). "Finally, we examined the impact of NEK8 mutations identified in patients in zebrafish, an in vivo model relevant for ciliopathies." (PMID 26967905, 2016). "Similarly, NEK8, a kinase implicated in ciliopathy, harbors an RCC1-repeat region." (PMID 41154634, 2025). "One important study contributed to the understanding of how NEK8, as well as its functions in DDR is linked to ciliopathies." (PMID 32294979, 2020). "NEK8, like other proteins involved in ciliopathies, has recently been described as a regulator of DNA damage response (DDR), with loss of NEK8 dramatically affecting S-phase progression upon DNA stress conditions." (PMID 26967905, 2016). "Moreover, due to the widespread presence of primary cilia in various tissues, NEK8-related ciliopathies can affect multiple organ systems, leading to complex syndromes that include liver fibrosis, retinal degeneration, and skeletal abnormalities." (PMID 41154634, 2025). "Several NEK family members, including NEK8 and NEK9, span multiple functional categories, as NEK8 has been linked to cancer and cell cycle control and NEK9 has been implicated in ciliogenesis and ciliopathies." (PMID 37099601, 2023). "However, the positive response of both Cep290 and Nek8 mutant cells (and other ciliopathy models ) to CDK inhibitors suggests a common aetiology." (PMID 28973549, 2017). "In zebrafish, injection of nek8 morpholinos led to ciliopathy-related phenotypes that could be rescued by wild-type nek8, but not by the mutated forms." (PMID 25974046, 2015). "Thus, therapies aimed at restoring NEK8 activity or compensating for its dysfunction could be transformative in managing ciliopathies." (PMID 41154634, 2025). "The role of NEK8 in ciliogenesis, which entails the formation of cilia important for cellular signaling and movement, is especially significant in PKD and related ciliopathies." (PMID 41154634, 2025). "Additionally, the transcriptional expression levels of several well-recognized cilia genes in the PBMCs, including CEP131, NEK8 and other cilia genes recorded in the SCGSv2 gold standard list, were substantially elevated in the genome-wide transcriptome profile of EVC ciliopathy patients." (PMID 37326025, 2023).
nephronophthisis (9 papers, 2012 to 2025). Progressive tubulointerstitial injury, inherited in an autosomal recessive pattern, caused by mutations in genes involved in ciliary function, which may result in an end stage renal failure. "NEK8 has been reported to be associated with ciliary and centrosome localization and nephronophthisis." (PMID 37835513, 2023). "In summary, replication stress, activation of CDK and depletion of NEK8 may contribute to the development of nephronophthisis (NPHP)." (PMID 32294979, 2020). "More recently, localisation of ANKS6 to the primary cilium and interactions between ANKS6 and proteins involved in nephronophthisis (INVS, NHPH3, NEK8) were demonstrated." (PMID 26327442, 2015).
polycystic kidney disease (9 papers, 2007 to 2022). A usually autosomal dominant and less frequently autosomal recessive genetic disorder characterized by the presence of numerous cysts in the kidneys leading to end-stage renal failure. "Mutations that cause nephronophthisis are present within the same region of the RCC1 domain of Nek8 as those that cause polycystic kidney disease in jck mice." (PMID 35409400, 2022). "It is of interest that the mouse and rat mutations in Nek8/NPHP9 lead to a phenotypic presentation of polycystic kidney disease that resembles human ARPKD, with an early onset, enlarged cystic phenotype and widespread cyst development." (PMID 22899815, 2012). "Established mouse models of polycystic kidneys have been shown to have mutations in the Nek8 gene." (PMID 32294979, 2020). "Similarly, a mutation in the RCC1 domain of Nek8 leads to polycystic kidney disease in rats." (PMID 35409400, 2022). "The Nek8 gene was originally identified and cloned in jck mice as responsible for polycystic kidney disease." (PMID 35409400, 2022). "The expression products of AIX and Nek8 participate in the occurrence of polycystic kidney and renal cell carcinoma, by affecting cilia function." (PMID 35448166, 2022). "The same limitations are found in the Lewis polycystic kidney (LPK), Wistar polycystic kidney (Wpk) and Cy rat models, with mutations in the orthologs of human NEK8/NPHP9, TMEM67/NPHP11 and ANKS6/NPHP16 genes, respectively." (PMID 34055783, 2021). "NEK8 is expressed in various brain regions including cerebellar nuclei and is thought to play a role in fetal organ development and polycystic kidney disease." (PMID 27120335, 2016). "Of the mammalian Neks, both Nek1 and Nek8 were unexpectedly implicated in cilia function when it was found that mutations in laboratory mouse models of polycystic kidney disease (PKD) mapped to the Nek1 and Nek8 genes." (PMID 17727698, 2007). "The DDR signaling marker, γH2AX, was markedly increased in some polycystic kidney models and one of the genes involved in DDR, NEK8, appeared to work through downstream signaling in the inv mutant model." (PMID 29889867, 2018).
gastric cancer (7 papers, 2020 to 2025). A primary or metastatic malignant neoplasm involving the stomach. "Several members of the NIMA-related kinase (NEK) family have been implicated in tumor progression; however, the role and underlying mechanisms of NEK8 in gastric cancer (GC) remain unclear." (PMID 39762761, 2025). "Additionally, high expression levels of NEK8 in gastric cancer patients are associated with poor survival rates." (PMID 32294979, 2020). "A recent pilot study on stomach cancer suggested that NEK8 promotes GC cell proliferation, but the downstream targets and mechanisms of NEK8 in carcinogenesis were not addressed." (PMID 39762761, 2025). "This demonstrated that NEK8 has an important role in gastric cancer progression and its regulation by pVHL, and this finding has contributed to the development of new therapeutic strategies." (PMID 32294979, 2020). "In vivo, NEK8 depletion inhibited gastric cancer cell growth." (PMID 32294979, 2020). "Furthermore, it has been reported that NEK8 may potentially play the role of an oncoprotein in human gastric cancer through the HIF-1 signalling pathway." (PMID 37100815, 2023). "Additionally, NEK8 reportedly has varying effects on the progression of different diseases and has been shown to positively enhance the proliferation and migration capabilities of gastric cancer cells." (PMID 37596667, 2023). "Furthermore, NEK8 has been found to facilitate the proliferation of gastric cancer cells." (PMID 37596667, 2023).